TMEM125 (transmembrane protein 125)
Synonyms: MGC17299
Tractability: Antibody: UniProt predicts a signal peptide or a membrane-spanning region.
Gene: Protein-coding gene on chromosome 1 (43,269,979 to 43,274,007, forward strand). Ensembl gene ENSG00000179178.
Subcellular location: Membrane
Subcellular location (Human Protein Atlas): Cytosol; Midbody
Gene Ontology:
Cellular component: membrane
Genetic constraint (gnomAD): Loss-of-function variants: 11 observed, 6.74 expected, observed/expected ratio (o/e) 1.63, 90% interval 0.97 to 1.95. That is too few expected variants to judge how well the gene tolerates losing a copy. Missense variants: 270 observed, 291.38 expected, observed/expected ratio (o/e) 0.93, 90% interval 0.84 to 1.02. Synonymous variants: 144 observed, 137.28 expected, observed/expected ratio (o/e) 1.05, 90% interval 0.92 to 1.21.
Homologues: Orthologues: chimpanzee TMEM125 (100% identical), macaque TMEM125 (99% identical), rabbit TMEM125 (89% identical), guinea pig TMEM125 (87% identical), pig TMEM125 (87% identical), rat Tmem125 (86% identical), mouse Tmem125 (86% identical), tropical clawed frog tmem125 (43% identical), zebrafish tmem125b (32% identical).
Diseases named in the same sentence as TMEM125 in open-access papers:
TMEM125 is named in the same sentence as 4 diseases in open-access papers, as found by Europe PMC text mining. Sharing a sentence is not in itself a finding about the gene and the disease. The quoted sentences say what the papers report.
cervical cancer (1 paper, 2022). A primary or metastatic malignant neoplasm involving the cervix. "In the present study, the immune subtype-relevant signature (covering TMEM125, TFF1, DECR2, LONRF3, DAPL1, and ANKRD35) was quantified, which predicted cervical cancer recurrence accurately and independently." (PMID 36313466, 2022).
Obesity (1 paper, 2022). Accumulation of substantial excess body fat. "Seven of the genes were downregulated by obesity and reversed by VSG specific weight loss including Ido1, Aldoc, Tmem125, Dgki, Slc7a4, Msc, and Ephb3, while four were inversely regulated with obesity elevating Klhl5, Nek6, Arhgap20, and Hp." (PMID 35775614, 2022).
cancer (2 papers, 2019 to 2022). A tumor composed of atypical neoplastic, often pleomorphic cells that invade other tissues. "The genes that had a high expression when compared to the control group, low standard deviation and repeat in multiple cancer types are TMEM125,C1orf172 and KLHL9." (PMID 31831960, 2019). "TMEM125, C1orf172 andKLHL9 are the 3 genes that are found in more than one cancer type." (PMID 31831960, 2019). "CD36, PDK4, and THBS1 were highly expressed in cancer tissues, and G3BP2, PTPRB, and TMEM125 were lowly expressed in cancer tissues." (PMID 36147333, 2022). "CD36, THBS1, and PDK4 were highly expressed in cancer tissues, whereas PTPRB, G3BP2, and TMEM125 were lowly expressed in cancer tissues." (PMID 36147333, 2022).
TMEM125 also shares sentences with these, for which no sentence is quoted: tumour (1 paper).